IGLV3-25 (immunoglobulin lambda variable 3-25)
Description:
V region of the variable domain of immunoglobulin light chains that participates in the antigen recognition. Immunoglobulins, also known as antibodies, are membrane-bound or secreted glycoproteins produced by B lymphocytes. In the recognition phase of humoral immunity, the membrane-bound immunoglobulins serve as receptors which, upon binding of a specific antigen, trigger the clonal expansion and differentiation of B lymphocytes into immunoglobulins-secreting plasma cells. Secreted immunoglobulins mediate the effector phase of humoral immunity, which results in the elimination of bound antigens. The antigen binding site is formed by the variable domain of one heavy chain, together with that of its associated light chain. Thus, each immunoglobulin has two antigen binding sites with remarkable affinity for a particular antigen. The variable domains are assembled by a process called V-(D)-J rearrangement and can then be subjected to somatic hypermutations which, after exposure to antigen and selection, allow affinity maturation for a particular antigen.
Synonyms: IGLV325; V2-17
Tractability: Antibody: its Gene Ontology location is reachable by antibodies, with high confidence; UniProt places it where antibodies can reach, with medium confidence; UniProt predicts a signal peptide or a membrane-spanning region.
Gene: Immunoglobulin variable (V) gene on chromosome 22 (22,686,726 to 22,687,271, forward strand). Ensembl gene ENSG00000211659.
Subcellular location: Secreted; Cell membrane
Pathways (Reactome):
Immune System: Antigen activates B Cell Receptor (BCR) leading to generation of second messengers; CD22 mediated BCR regulation; Classical antibody-mediated complement activation; FCERI mediated Ca+2 mobilization; FCERI mediated MAPK activation; FCERI mediated NF-kB activation; FCGR activation; Fc epsilon receptor (FCERI) signaling; Immunoregulatory interactions between a Lymphoid and a non-Lymphoid cell; Initial triggering of complement; Regulation of Complement cascade; Regulation of actin dynamics for phagocytic cup formation; Role of LAT2/NTAL/LAB on calcium mobilization; Role of phospholipids in phagocytosis
Disease: FCGR3A-mediated IL10 synthesis; FCGR3A-mediated phagocytosis; Potential therapeutics for SARS
Hemostasis: Cell surface interactions at the vascular wall
Vesicle-mediated transport: Scavenging of heme from plasma
Gene Ontology:
Molecular function: antigen binding
Biological process: immune response
Cellular component: blood microparticle; extracellular region; immunoglobulin complex; plasma membrane
Homologues: Orthologues: chimpanzee IGLV3-25 (83% identical), tropical clawed frog igl (56% identical). Paralogues in human: IGLV3-16 (94% identical), IGLV3-10 (88% identical), IGLV3-27 (87% identical), IGLV3-1 (80% identical), IGLV3-22 (78% identical), IGLV3-19 (73% identical), IGLV3-21 (73% identical), IGLV3-9 (73% identical), IGLV3-12 (70% identical), IGLV3-32 (68% identical), IGLV1-40 (62% identical), IGLV2-18 (62% identical), and 81 more.